CCNE1 (cyclin E1)
Diseases named in the same sentence as CCNE1 in open-access papers (continued):
Sharing a sentence is not in itself a finding about the gene and the disease.
ovarian carcinoma (continued). "Cyclin E1‐driven ovarian cancer (OvCa) is characterized with metabolic shift." (PMID 31657115, 2019). "Accordingly, Cyclin E (CCNE1) amplification is a known trait in ovarian cancers with intact HR." (PMID 31491988, 2019). "column 6) paths containing three known ovarian cancer oncogenes CCNE1, AURKA and RAB2534–36." (PMID 30944378, 2019). "Cyclin E1‐driven ovarian cancer shows metabolic shift that is mediated by GCN5/PGC‐1α axis." (PMID 31657115, 2019). "Attenuation of the PI3K/PKCiota/cyclin E1 pathway is a target in ovarian cancer." (PMID 28211159, 2017). "The following genes were overexpressed in various tumors: CCND1 in colorectal and renal cancers, and sarcoma; CCNE1 in colorectal, lung, stomach, esophagus, head and neck, uterine and ovarian cancers, and sarcoma; and CDKN2A in lung, uterine, and ovarian cancers." (PMID 28258440, 2017). "Importantly, CCNE1 gene amplification correlates with CCNE1 overexpression in ovarian cancer and appear to have poorer disease-free and overall survival." (PMID 26204491, 2015). "We thus hypothesized that ovarian cancer cells with elevated CCNE1 expression would be more sensitive to the suppression of Cdk2 activity." (PMID 26204491, 2015). "Consequently, loss of BRCA1 is synthetic lethal to cells harbouring CCNE1 amplifications, and this has recently been validated using inhibition of BRCA1-mediated DNA repair in ovarian cancer cell lines." (PMID 26427375, 2015). "Our finding that some ovarian cancer cells are addicted to the presence of CCNE1 indicates that CCNE1 may be a driver oncogene to initiate ovarian cancer." (PMID 26204491, 2015). "Several studies suggested that CCNE1 may represent a useful prognostic marker and has the potential to be a target for therapy in breast and ovarian cancer." (PMID 26121660, 2015). "Our data show that CCNE1 gene amplification is present in majority of ovarian cancer cell lines with elevated CCNE1 overexpression, thus indicating that CCNE1 gene amplification is at least one of the principal factors contributing to CCNE1 overexpression in ovarian cancer." (PMID 26204491, 2015). "To determine if elevated CCNE1 expression is linked to CCNE1 gene amplification in ovarian cancer, we initially examined the level of CCNE1 mRNA and protein in a panel of established ovarian cancer cell lines, immortalized ovary epithelial cells (OECs) and FTSECs." (PMID 26204491, 2015). "The observation that Cdk2 inhibitor SNS-032 selectively induces apoptosis in ovarian cancer cells with elevated CCNE1 expression prompted us to investigate its efficacy to suppress ovarian tumor progression with the well-established ovarian tumor peritoneal metastatic colonization model." (PMID 26204491, 2015). "Recent study showed that ovarian cancer cells overexpressing CCNE1 exhibited greater Cdk2 activity." (PMID 26204491, 2015). "We hypothesize that of the currently available CDKi, Dinaciclib may have the best therapeutic potential in cyclin E1-dependent ovarian cancer." (PMID 24624361, 2014). "Amplification of CCNE1 in ovarian cancer correlates with drug resistance and poor clinical outcome." (PMID 22355333, 2012). "Amplicon-dependent expression of CCNE1, together with the genes POP4, PLEKHF1, C19orf12 and C19orf2 that flank CCNE1 on this segment, was linked with primary treatment failure in ovarian cancer, possibly due to rapid repopulation of the tumor after chemotherapy." (PMID 22291905, 2012). "Similarly, Wang et al22 in their meta-analysis concluded that CCNE1 is a negative prognostic factor and is associated with poor overall survival in ovarian cancer patients." (PMID 37250533, 2023). "In this group of HGSC cases with known CCNE1 amplification, amplification largely appears conserved across metastatic sites of disease consistent with its presumed role as a truncal driver event, based on the occurrence of CCNE1 amplification in ovarian cancer precursor lesions." (PMID 34485660, 2021).
ovarian carcinoma (continued). "This is in agreement with a recent study in ovarian cancer that demonstrated that reduction of CCNE1 expression significantly inhibited cell growth in CCNE1 expressing cells, with a more profound effect in ovarian cancer cells harbouring CCNE1 gene amplification." (PMID 22433433, 2012). "CCNE1 amplification is prevalent in primary PROC and WEE1 kinase inhibitors show a manageable toxicity profile and encouraging efficacy in epithelial ovarian cancer harboring CCNE1 amplification." (PMID 41376855, 2026). "HGSOC cells exhibiting CCNE1 amplification display elevated CDK2 expression, and reducing or inhibiting CDK2 leads to decreased ovarian cancer cell proliferation." (PMID 38255960, 2024). "This was further highlighted in the CCNE1-stratified IGNITE trial of recurrent, platinum-resistant ovarian cancer; the ORR was 38% in over-expressed and amplified tumours and 45% in over-expressed only tumours." (PMID 39135999, 2024). "More recently, CCNE1 amplification has been proposed as a potential biomarker indicative of response to combined WEE1 inhibition and ATR inhibition in preclinical ovarian cancer and endometrial cancer models." (PMID 37457127, 2023). "We chose the ovarian cancer cell line OVCAR-3, where prior work has established via in vitro and in vivo genetic knockdown experiments that growth of OVCAR-3 cells is driven by cyclin E1 overexpression and dependent on CDK2." (PMID 37270540, 2023). "In a cohort-wide analysis, multiple genomic regions containing recurring amplifications and deletions were identified, encompassing copy number gains in genes marked as drivers in ovarian cancer such as MYC and CCNE1." (PMID 35326660, 2022). "Knockdown of the CCNE1 and CDK2 genes in known CCNE1 amplified ovarian cancer cell lines has led to reduced clonogenic survival, but this has not been seen with the CDK2 inhibitor daniciclib when given as monotherapy." (PMID 34485660, 2021). "Here, we review the current understanding of one of the most common genetic alterations in epithelial ovarian cancer, CCNE1 (cyclin E1) amplification, and its role as a potential predictive marker of cytotoxic chemotherapy resistance." (PMID 32380689, 2020). "Using data from TCGA and GTEX, the mRNA expression levels of RECQL4, PRKCL, CCNE1, and ETV5 were found to be increased in ovarian cancer compared to normal FT tissues." (PMID 33014878, 2020). "Other notable DMGs include key markers of ovarian cancer such as MUC16 (CA-125) and PAX8, as well as genes that play key roles in ovarian cancer biology such as CCNE1 and MTHFR." (PMID 31870409, 2019). "Co-treatment of VPA with DOX led to synergistic suppression of cell viability with an increase in caspase-3 activity and CDKN1A, CCNE1, PARP1, and PARP3 proteins expression in ovarian cancer cell lines." (PMID 28498322, 2017). "For example, CDKN2B and CDK4 as well as EGFR and NF1 are involved in the RB and RTK signaling pathways, respectively and the CCNE1, MYC and RAD52 module in ovarian carcinoma is involved in cell cycle." (PMID 24565034, 2013). "High-levels of CCNE1 protein, an activating subunit of the cyclin dependent kinase 2 (CDK2), are often observed in patients with ovarian cancer." (PMID 22355333, 2012). "We therefore attempted to illustrate these genomic and epigenetic sample irregularities (such as observed in PLAGL1, CCNE1 and PIAS3) for many of the known ovarian cancer genes." (PMID 22174824, 2011). "Prior research has revealed that HGSOC cells with CCNE1 amplification display elevated CDK2 expression, and reducing or inhibiting CDK2 could lead to decreased ovarian cancer cell proliferation." (PMID 38255960, 2024). "To address this hypothesis, we have comprehensively evaluated the clinicopathological significance of the CDK2, CDK4, CDK6, cyclin D1, cyclin E1, RB1 and pRB1(Ser 795) protein expression in a clinical cohort of epithelial ovarian cancer." (PMID 38612869, 2024).
ovarian carcinoma (continued). "Blocking PKMYT1 activity was effective in eradication of CCNE1-amplified ovarian cancer cells, but not cell lines without amplification through preventing completion of DNA synthesis and increasing the rates of premature mitotic entry." (PMID 38279263, 2024). "Our control methods of using non-tumor tissue from CCNE1-amplified cases as well as non-CCNE1-amplified ovarian cancer cases helps to correctly identified CCNE1 amplification." (PMID 34485660, 2021). "Together, we deduced that MED12, LRP2, PIK3R2, CCNE1, and LRP1B might be potential biomarkers for immunotherapy of ovarian cancer." (PMID 33432021, 2021). "Moreover, we recently demonstrated that reduced expression of SKP1, CUL1 and RBX1 prevents Cyclin E1 degradation leading to an increase in abundance that induces CIN and promotes cellular transformation in colorectal and ovarian cancer contexts." (PMID 35008511, 2021). "In this subset of patients, it was found that cyclin E1 immunohistochemistry did not predict taxane-platinum chemoresistance in ovarian cancer patients." (PMID 32380689, 2020). "In this study, 73 OV marker genes were discovered to have emerged in the origin of the first cell (PS1 and PS2), including CCNE1-amplified high-grade serous ovarian cancer (HGSC) dependent kinase CDK287 and the oncogenic capacity of advanced-stage ovarian cancer enhancing protein PRKAB188." (PMID 30796309, 2019). "CCNE1 is closely related to the occurrence and development of many tumors such as epithelial ovarian cancer, inflammatory breast cancer, non-muscle invasive bladder cancer, colorectal cancer, ovarian clear cell carcinoma, hepatomegaly, osteosarcoma, glioma." (PMID 31072916, 2019). "Further, a series of genes, such as cyclin E1 (CCNE1), cyclin B2 (CCNB2), cytochrome P450 family 3 subfamily A member 5 (CYP3A5), and vascular endothelial growth factor A (VEGFA), have been predicted as target genes for diagnosing ovarian cancer." (PMID 29482638, 2018). "Yet, CCNE1 amplification in breast and ovarian cancers does not lead to the rearrangement phenotype that we observed in CCN-HCC." (PMID 30531861, 2018). "On a functional level, URI but not CCNE1 enhanced the viability of ovarian cancer cell lines in a high-throughput siRNA screen." (PMID 27582547, 2017). "Our results indicate that CCNE1 immunohistochemistry does not predict taxane-platinum chemoresistance in ovarian cancer patients." (PMID 28977941, 2017). "CCNE1 is another therapy target, and it is found to be over-expressed in endometrial carcinomas, bladder carcinoma, ovarian cancer and non-BRCAness high grade ovarian carcinoma." (PMID 28178664, 2017). "An obvious feature of ovarian cancer is the presence of recurrent regions of copy number gains or losses, and rare recurrent genomic events contain known oncogenes, such as MYC and CCNE1 in our analysis." (PMID 26735889, 2016). "This uncovers a 40-fold difference in the sensitivity to Cdk2 inhibitor between ovarian cancer cell lines with and without CCNE1 overexpression (P = 0.003)." (PMID 26204491, 2015). "Since CCNE1 gene is not amplified in OCC1 cells, these results suggest that the presence of CCNE1 is critically important for the growth of ovarian cancer cells with elevated CCNE1 expression regardless of CCNE1 gene amplification status." (PMID 26204491, 2015). "Comparing to that in OECs or FTSECs, CCNE1 gene was not amplified in ovarian cancer cell lines without CCNE1 overexpression." (PMID 26204491, 2015). "Ovarian cancer cells with elevated CCNE1 expression were 40 times more sensitive to Cdk2 inhibitorSNS-032 than those without inherent CCNE1 overexpression." (PMID 26204491, 2015).
ovarian carcinoma (continued). "IC50s of OECs and FTSECs in a 4-day treatment period were 25.21 and 31.44 μM respectively, resembling to those observed in ovarian cancer cells without CCNE1 overexpression." (PMID 26204491, 2015). "Additionally, for ovarian cancer it was shown that TERT and MYC, as well as PIC3CA, CCNE1, and KRAS, might be useful to tailor therapeutics in precision medicine, and the same might be true for lung cancer." (PMID 37858127, 2023). "Interestingly, proteins such as CCNE1, FASN, HDGF, MCM7, PIGR, PTK2, or TRA2B have been described as having a prognostic relation with some other type of gynecological cancer (breast, cervical or ovarian cancer)." (PMID 34680205, 2021). "Thus, CCNE1 amplification, but not cyclin E1 overexpression, is a more reliable predictive biomarker of chemotherapy resistance in epithelial ovarian cancer." (PMID 32380689, 2020). "CCNE1 copy number gains revealed a different subtype of ovarian carcinoma and could be used as a negative selection marker for platinum therapy and PARP inhibitors." (PMID 31060523, 2019). "We and others have recently shown that URI (C19orf2) is amplified in a subset of ovarian carcinomas and ovarian cancer cell lines, suggesting that CCNE1 may not be the exclusive driver at 19q12." (PMID 27582547, 2017). "This possibility is clearly supported by our observation that the growth of ovarian cancer cell lines with CCNE1 overexpression are greatly inhibited by CCNE1 knockdown while CCNE1 siRNAs did not significantly alter the growth of lines without CCNE1 overexpression." (PMID 26204491, 2015). "However, CCNE1 siRNAs did not significantly alter the growth of ovarian cancer cell lines without CCNE1 overexpression (ES2, OVCAR429, IGROV1, SK-OV3)." (PMID 26204491, 2015). "However, our in vitro studies with established ovarian cancer cell lines failed to establish a correlation between CCNE1 expression and tumorigenic potential." (PMID 26204491, 2015). "In addition to BRCA1, the shRNA screen identified the DNA repair genes ATR and XRCC2 as specific genetic hits in CCNE1-amplified cell lines, suggesting that inhibition of the DDR may be a therapeutic strategy in CCNE1-amplified ovarian cancer." (PMID 24624361, 2014). "Additionally, Affymetrix SNP 6.0 data obtained from the TCGA ovarian cancer study was also evaluated for independent breakpoints affecting TSHZ3 in the absence of CCNE1 amplification." (PMID 22514011, 2012). "Finally, regarding the timing of these events in ovarian cancer, it is known that FOXM1 is expressed in HGSC precursor lesions in the FTE, which may, along with other proteins such as cyclin E1, increase RS, thus providing a selective advantage for RHNO1 co-expression." (PMID 33890574, 2021). "MTT assay showed that OVCAR429 was the most sensitive line to JNJ-7706621 among ovarian cancer cell lines without CCNE1 overexpression which had an IC50 of 0.55 μM while OVCAR5 was the least sensitive line among ovarian cancer cell lines with elevated CCNE1 expression which had an IC50 of 2.02 μM." (PMID 26204491, 2015). "Similarly, ovarian cancer cell lines without CCNE1 overexpression could also be either metastatic or non-metastatic (P = 0.933between with and without CCNE1 overexpression)." (PMID 26204491, 2015). "We also analyzed PIK3CA, a frequently amplified oncogene in ovarian cancer, and observed that PIK3CA and CCNE1 amplification are not mutually exclusive." (PMID 37519629, 2023). "In contrast, IC50 of SNS-032 in ES2, the most sensitive ovarian cancer cell line among those without CCNE1 overexpression was 20.05 μM while IC50 of SNS-032 in OVCAR3, the least sensitive one among those with elevated CCNE1 expression was 0.53 μM." (PMID 26204491, 2015). "Furthermore, we confirmed that protein levels of ASF1B, CCNE1, CDC20, and RNASEH2A were significantly increased in ovarian cancer cells compared with non-transformed ovarian cells." (PMID 39199556, 2024).
ovarian carcinoma (continued). "Although not correlated with CCNE1 expression in our analysis, co-amplification of ID1 with CCNE1 may further contribute to cell cycle de-regulation in ovarian cancer." (PMID 21103391, 2010). "To determine the effect of Cdk2 inhibitor on ovarian cancer cell growth, we showed that ovarian cancer cells with elevated CCNE1 expression are at least 40 times more sensitive to Cdk2 inhibitor SNS-032 than those without CCNE1 overexpression, immortalized OECs and FTSECs." (PMID 26204491, 2015).